NKILA (NF-kappaB interacting lncRNA)
Diseases named in the same sentence as NKILA in open-access papers (continued):
Sharing a sentence is not in itself a finding about the gene and the disease.
tumor (continued). "Given the involvement of NKILA in the TGF-β signaling, which plays a vital role in cell migration and invasion, we speculated that NKILA plays an important role in tumor metastasis." (PMID 29379981, 2018). "NKILA was significantly downregulated in tumor tissues compared with that in normal tissues." (PMID 29348395, 2018). "Knockdown of LINC00673, MALAT1 and UCA1, and overexpression of MEG3 and NKILA can inhibit tumor progression, which might become prospective treatment methods." (PMID 29416703, 2018). "The tumor suppressive roles of NKILA were further investigated in a xenografted nude mice model." (PMID 29348395, 2018). "Additionally, low NKILA expression is significantly correlated with advanced clinical stage, tumor size and lymph node metastasis in TSCC." (PMID 29416703, 2018). "In addition, NKILA expression levels were significantly decreased in advanced tumor tissues compared with early stage tumor tissues (p < 0.01)." (PMID 29379981, 2018). "Moreover, the prognostic value of NKILA expression in selective patient subgroups stratified by clinical stage, tumor size and lymph node status was analyzed." (PMID 27613832, 2016). "Notably, a few lncRNAs such as Linc-pint, MBNL1-AS1, and NKILA may function as tumor suppressors by cooperating with TGFβ signaling during early tumorigenesis, although direct stage-specific evidence remains limited and warrants further investigation." (PMID 41437175, 2025). "Moreover, knockdown of NKILA significantly inhibits tumor growth by increasing the CTLs in tumor." (PMID 31850199, 2019). "Accordingly, NKILA overexpression correlates with CTL apoptosis and poor survival in lung cancer, while its knockdown enhances tumor clearance in patient-derived xenografts." (PMID 41409273, 2025). "NKILA (NF-κB Interacting LncRNA) is significantly downregulated in ESCC tissues and its low expression is negatively correlated with tumor stage, lymph node metastasis, and clinical severity." (PMID 41437175, 2025). "NKILA levels were significantly lower in ES2C cells, compared to the parental ES2 cells, which suggested that this lncRNA is a tumor suppressor lncRNA and relates inversely with cisplatin resistance." (PMID 38745302, 2024). "It was shown that the expression levels of NKILA, and NBAT1 lncRNAs were related to tumor size, and BC040587 expression level related to age, node metastasis, tumor size, and grade (p < .05)." (PMID 36274054, 2023). "Therefore, NKILA could exert a context-dependent role as a regulator of NFκB signaling and metastasis, suggesting the potential of this lncRNA as a therapeutic target to modulate the function of tumor-specific T cells in BC." (PMID 37342324, 2023). "The expression level of NKILA lncRNA remains low in OSCC and it is correlated to tumour size, clinical staging, and metastasis." (PMID 36428681, 2022). "In LUAD patients, we found that AC022613.1 was strongly connected with the tumor stage and GSEC, LINC00941, and NKILA were significantly connected with immune subtypes." (PMID 35368654, 2022). "Firstly, we showed that NKILA was methylated in NHL cell lines and NHL primary samples, but unmethylated in normal controls, hence methylated in a tumor-specific manner in NHL." (PMID 35052468, 2022). "In a study concerning OS, researchers learned that NKILA expression in OS tissues is strikingly reduced, with its level lower in stage III tumor tissues than that in stage I‐II." (PMID 32249459, 2020). "The study demonstrated that reducing the activity of NKILA intensifies the infiltration of CTL which results in the inhabitation in the expansion and development of the tumor." (PMID 32851072, 2020). "LncRNAs can function either as oncogenes (e.g., HOTAIR, MALAT1, H19) or as tumor suppressors (e.g., HOTAIRM1, NKILA, XIST) by targeting genes that foster or prevent tumor development and progression, respectively." (PMID 33049922, 2020).
tumor (continued). "qRT-PCR was used to analyze mouse tumor tissues and confirmed the effects of decreasing the levels of NKILA in the LN229-K.D.-NKILA group." (PMID 32382013, 2020). "According to clinicopathological feature analysis, lower NKILA expression was observed more frequently in patients with advanced TNM stages (P = 0.002) and larger tumor size (P = 0.005)." (PMID 29573243, 2018). "In this study, we aimed to investigate the role of NKILA in TGF-β pathway, regulating the NF-κB activity and tumor cell EMT in NSCLC, as well as the clinical significance of NKILA in predicting lymph node metastasis." (PMID 28412955, 2017). "In addition, through rescue experiments, we demonstrated that MTX1 overexpression reversed NKILA silencing‐suppressed tumor growth, cell viability, EMT, and Warburg effect, and NKILA silencing‐enhanced apoptosis and autophagy." (PMID 41498025, 2025). "NKILA inhibition in tumor-infiltrating lymphocytes and CAR T cells may silence their activation-induced cell death, thus suppressing tumor immune evasion and expanding the efficacy of cancer immunotherapy." (PMID 35189921, 2022). "The expression of NKILA in NSCLC tissues is downregulated than adjacent noncancerous tissues, and low-expressed NKILA in tumor tissues is closely related to the advanced tumor-node-metastasis (TNM) stage and lymph node metastasis." (PMID 35237359, 2022). "In the NF-kB signaling pathway, lncRNA NKILA can interact with NF-kB, participating in the negative feedback regulation of NF-kB, and acts as a tumor suppressor gene in BC." (PMID 34135756, 2021). "NKILA silencing in the transferred TILs and CAR T cells may overcome tumor immune evasion by inhibiting their AICDs, and improve the efficacy of adoptive T cell therapy for cancers." (PMID 32083005, 2020). "NKILA is induced in activated T cells by STAT1 (signal transducer and activator of transcription 1) in a calcium/calmodulin-dependent fashion and promotes AICD in tumor-specific cytotoxic T lymphocytes and T helper cells type 1 (TH1) via the inhibition of the NF-κB pathway." (PMID 37782337, 2024). "NKILA expression levels in tumor tissues and matched adjacent normal tissues from 39 patients with ESCC were measured by RT-qPCR, which showed that NKILA expression was significantly reduced in ESCC tissues compared with adjacent normal esophageal tissues (p < 0.001)." (PMID 29379981, 2018). "NKILA can inhibit NF-κB activation by suppressing IKK-induced IĸBα phosphorylation but not IKK activity, resulting in the repression of tumor cell migration and invasion." (PMID 29416703, 2018). "We found that NKILA, a TGF-β-induced lncRNA, is also involved in these negative-feedback networks and serves as tumor suppressor by inhibiting ESCC progression and metastasis." (PMID 29379981, 2018). "Moreover, NKILA expression levels, which were remarkably reduced in ESCC tumor tissues compared with adjacent noncancerous tissues, were negatively correlated with TNM stages and lymph node metastasis (no statistical significance)." (PMID 29379981, 2018). "Although NKILA does not directly regulate canonical TGFβ-Smad signaling, its inhibition of NF-κB signaling may interact with or counterbalance TGFβ-induced EMT and inflammatory responses, reflecting a broader antagonism to tumor-promoting signaling cascades." (PMID 41437175, 2025).
cancer (36 papers, 2016 to 2025). A tumor composed of atypical neoplastic, often pleomorphic cells that invade other tissues. "Moreover, NKILA underexpression was shown to be an effective prognostic and diagnostic biomarker in human cancer." (PMID 34202021, 2021). "Cancer cells are usually highly proliferating cells and we checked the effect of NKILA on cell proliferation." (PMID 38745302, 2024). "Overexpressing NKILA attenuated cancer metastasis and tumorigenesis by blocking the translocation of NF-κB component p65 from the cytoplasm into the nucleus and inhibiting the phosphorylation of IκBα, thereby downregulating NF-κB signalling." (PMID 40176927, 2024). "A phase 2, single arm clinical trial showed that high expression of NF-κB-interacting lncRNA, NKILA, in cancer cells or cancer-specific CTLs predicted a poor prognosis among cancer patients treated with immunotherapy." (PMID 37767098, 2023). "LIMIT is an immunogenic lncRNA in cancer immunity targetable for cancer immunotherapy, while NKILA, another lncRNA, can promote tumor immune evasion by sensitizing T cells and activate induced cell death." (PMID 36071454, 2022). "Six NETs-related lncRNAs (AF131215.5, MYOSLID, NKILA, AC090152.1, SNHG10, and TRG.AS) have been reported to be associated with cancer progression." (PMID 34257164, 2021). "LncRNA NKILA is a previously documented regulator, functionally involved in multiple pathological processes, such as cancer and immunity." (PMID 31657882, 2020). "The work done in the present study is aimed at fulfilling an organized review and performing a quantitative meta-analysis to investigate the relationship between the expression level of NKILA and various forms of cancers occurring in humans." (PMID 32851072, 2020). "The aim of the present meta-analysis was to investigate the relationship between NKILA expression level and pathological attributes in human cancers." (PMID 32851072, 2020). "The collective results of seven studies involving 767 patients were used to evaluate the effect of NKILA overexpression on OS in various cancers." (PMID 32851072, 2020). "As EMT is closely related with metastasis of cancer cells 21, we further studied the connection of NKILA and EMT in HCC." (PMID 32015685, 2020). "As NF-κB is a critical link between liver inflammation and cancer 28, 29, it is essential to figure out the precise role of NKILA and its interaction with NF-κB in HCC." (PMID 32015685, 2020). "In the result of this meta-analysis, decreased NKILA expression is typical of different kinds of cancer." (PMID 32851072, 2020). "While, another lncRNA, NKILA, has been proved to be decreased in HCC tissues, and increasing the expression of NKILA significantly enhances the anti-cancer effects of baicalein in HCC though targeting to its downstream targets." (PMID 32595415, 2020). "Based on the algorithmic meta-analysis, the results obtained from the present study indicate that cancer patients with a low level of NKILA expression have shorter OS." (PMID 32851072, 2020). "The results revealed that NKILA was significantly decreased in all the cancer cells compared with that in NE1 cells." (PMID 29348395, 2018). "Accordingly, we hypothesized that NKILA may promote Warburg effect in cancers via upregulating MTX1 and enhancing its interaction with TOMM40." (PMID 41498025, 2025). "Such specific role of this lncRNA has never been reported even though NKILA has been implicated in resistance mechanism in other cancers." (PMID 38745302, 2024). "Increased NKILA expression in T cells may aid cancer cells in escaping immunological destruction via activation-induced cell death." (PMID 35311149, 2022). "In this study, our data demonstrated that SPRY4-IT1 overexpression in cancer cells could be activated by NF-κB, which can also promote the expression of the lncRNA NKILA." (PMID 34163032, 2021). "This is an indication that NKILA might influence the start and growth of a cancer." (PMID 32851072, 2020).
cancer (continued). "For example, LncRNA NKILA can regulate the sensitivity of T cells to activation-induced cell death (AICD) by inhibiting NF-κB activity, thereby avoiding immune destruction of cancer cells." (PMID 36568152, 2022). "We then downloaded 33 cancer types to understand the function of the lncRNAs and selected AC022613.1, GSEC, LINC00941, and NKILA for further study." (PMID 35368654, 2022). "It is known that the function of TGF-β signaling in cancer biology can be regulated by specific lncRNAs, such as ANCR and NKILA." (PMID 32349718, 2020). "Together with published reports of cancer metastasis-related lncRNAs, such as lncRNA-ATB, SChLAP1, NKILA, and PNUTS, our study confirms the regulatory roles of lncRNAs in EMT and cancer metastasis." (PMID 30979372, 2019). "As previously reported in other type of cancers, our study indicated that NPC patients with high NKILA expression survived significantly longer (OS, P < 0.001) or longer DFS (P < 0.001)." (PMID 31430288, 2019). "On the other hand, both qPCR and western blot assays confirmed that NKILA suppressed activation of several NF-κB target genes including CCND1, TWIST1, MMP9 and XIAP, all of which play vital roles in cancer growth and metastasis." (PMID 29348395, 2018). "In this study, we showed that NKILA was downregulated in ESCC tissues and cancer cells compared with their normal counterparts." (PMID 29348395, 2018). "This study proved that NKILA suppressed autophagy‐related pathways by activating mTOR, decreased CD8+ T cell cytotoxicity, and consequently augmented PD‐L1 signaling that facilitated immune evasion in ICC cells and enhanced cancer progression." (PMID 41498025, 2025). "NKILA lncRNA can bind to NF-κB/IκB and shield the phosphorylation site of I-κB, thereby inhibiting IκB kinase (IKK)-induced I-κB phosphorylation, which in turn inhibits the activation of NF-κB proteins and suppresses cancer metastasis." (PMID 38782895, 2024). "Furthermore, NKILA also regulates TGFβ signalling and has been shown to decrease MMP14 levels in cancer, resisting cancer migration and metastasis." (PMID 40176927, 2024). "The expression profile of NKILA was detected in 137 paired ESCC cancer tissues and corresponding noncancerous tissues using qPCR assays, while GAPDH was used as the normalization control." (PMID 29348395, 2018). "Here we show that NKILA is down-regulated in TSCC cancer tissues than that in matched adjacent noncancerous tissues." (PMID 27613832, 2016). "In our study, we found NKILA was upregulated by classical TGF-β pathway and had higher expression level in early stages (TNM stageIandII) than advanced stages (TNM stage III and IV) of NSCLC (p = 0.048), which was consistent with the dual roles of TGF-β in cancer." (PMID 28412955, 2017). "Many of the well-studied lncRNAs, that are considered as regulatory molecules with various significant functions in cancer, have no junctions in their sequences such as MALAT1, NKILA, NEAT1 and NORAD." (PMID 34202021, 2021).
infection (1 paper, 2021). The state of being infected such as from the introduction of a foreign agent such as serum, vaccine, antigenic substance or organism. "NKILA expression was significantly increased in astrocytes after NKILA overexpression, validating the successful infection efficiency." (PMID 33686956, 2021).
inflammation (1 paper, 2021). Aberrant reaction of the microcirculation characterized by movement of fluid and leukocytes from the blood into extravascular tissues. "In this study, we aimed to investigate the potential role of NKILA in airway inflammation of children with MPP and the effect of NKILA on the secretory function of airway epithelial cells in vitro." (PMID 33855076, 2021).
vascular disorder (1 paper, 2021). A general term used to describe any disease affecting blood vessels]. "NKILA, a cytoplasmic lncRNA, was reported to have an interaction with NF-κB/IκB complex, indicating a role of NKILA as a crucial moderator to protect the endothelium from inflammatory lesions and associated vascular disorders." (PMID 34267668, 2021).
NKILA also shares sentences with these, for which no sentence is quoted: rectal cancer (2 papers); breast tumors (1); ductal carcinomas in-situ (1); glioblastoma (1); HIV-1 infection (1); immune dysfunction (1); intrahepatic cholangiocarcinoma (1); invasive carcinoma (1); liver cancer (1); lung adenocarcinoma (1); lymphoblastic leukemia (1); mantle cell lymphoma (1); osteoarthritis (1); osteosarcoma (1); periodontitis (1); peripheral T-cell lymphoma (1); renal carcinoma (1); rheumatoid arthritis (1); schizophrenia (1); skin cutaneous melanoma (1); small cell lung carcinoma (1).